TGFBI (transforming growth factor beta induced)
Diseases named in the same sentence as TGFBI in open-access papers (continued):
Sharing a sentence is not in itself a finding about the gene and the disease.
tumor (continued). "To further validate the function of TGFBI in GSC maintenance, we examined whether the exogenous recombinant human TGFBI (rhTGFBI) protein could promote GSC self-renewal and tumor growth." (PMID 35673564, 2022). "On the other hand, tumor cells tended to show higher expression of LY6E, FXYD5, and TGFBI." (PMID 35974387, 2022). "TGFBI was originally identified as a downstream effector of the TGF-β signaling pathway, a key network governing cell proliferation, differentiation, apoptosis, and migration, and playing a key role in tumor suppression in lymphoid cells." (PMID 35267594, 2022). "In addition, we explored the relationships of TGFBI expression with TME components and tumor stemness." (PMID 34671645, 2021). "Our results show that lack of TGFBI resulted in tumour vessel normalisation, with improved vessel perfusion and decreased hypoxia, a major factor controlling CSCs and metastasis." (PMID 33080107, 2020). "We next addressed the impact of TGFBI and TNC secreted by macrophages on tumor migration." (PMID 32312959, 2020). "On the other hand, a mechanistic link of TAM-secreted TNC and TGFBI with tumor migration, as identified in our study, has not been described as of yet." (PMID 32312959, 2020). "These secreted proteins were transforming growth factor beta induced (TGFBI), tenascin C (TNC), and fibronectin (FN1), which have in common that they are ECM proteins and as such may provide support for tumor cell adhesion and migration." (PMID 32312959, 2020). "These similarities may contribute to a functional cooperation of TGFBI and TNC in mediating tumor migration, when secreted by TAMs and other cells in the TME." (PMID 32312959, 2020). "RNAseq analysis of distinct anatomically defined tumor regions (e.g., leading edge, infiltrating region, necrotic zone, blood vessels etc.)and in situ hybridization for BIN1 (an MG-TAM marker) or TGFBI (a BM-TAM marker), revealed tumor geographic variation in TAM composition." (PMID 33154756, 2020). "In the present study, TGFBI was highly expressed in tumor tissues compared with adjacent non-tumor or normal tissues, showing a highest correlation with HNSCC." (PMID 31485443, 2019). "Combining a TGFBI inhibitor with other anticancer drugs may be an effective treatment strategy for gastrointestinal cancers that can preserve the tumor-suppressor effect of TGF-β signaling and TGFBI." (PMID 28106769, 2017). "TGFBI gene is a downstream target of transforming growth factor beta (TGF-β) that inhibits the proliferating of normal epithelial cells and functions as a tumor suppressor in early tumorigenesis as well as a tumor promoter in later stage of tumor progression." (PMID 22695319, 2012). "After implanting cells with TGFBI and leaving others without, we analyzed the onset, incidence, and volume of the resulting tumors in mice, in order to assess the tumor suppressive effect of TGFBI." (PMID 22695319, 2012). "Our results showed that there were significantly fewer ki67-positive cells in tumor tissues expressing TGFBI than in tissues without TGFBI." (PMID 22695319, 2012). "We did not observe any correlation between TGFBI expression and other clinico-pathological parameters analyzed such as gender, age or tumor histology." (PMID 20509890, 2010). "As expected, PCR bands were obtained for the tumor cell lines with TGFBI hypermethylation (H522, H810, H1417, DU145), but not for A549, PC3, and BEP2D cell lines." (PMID 18834524, 2008). "After treatment with TGF-β1 at 5 ng/ml for 6 h, induction of TGFBI mRNA level was not detectable in tumor cell lines with TGFBI hypermethylation, whereas A549, PC3, and BEP2D showed a high level of induction." (PMID 18834524, 2008). "TGFBI, also known as Betaig-h3, is a secreted protein induced by transforming growth factor-β (TGF-β) in human adenocarcinoma cells as well as in other human cell types, and has been shown to possess tumor suppressor function in in vitro studies." (PMID 18834524, 2008).
tumor (continued). "Furthermore, we found a negative correlation between Cat D and TGFBI expression in these tumor tissues." (PMID 38297161, 2024). "Furthermore, TGFBI, PLOD2 and APOL1 had clear tumor progression patterns in the TCGA-KIRC dataset." (PMID 38680858, 2024). "More importantly, a significant negative correlation between Cat D and TGFBI was observed in most tumor cases, suggesting that Cat D and TGFBI have crucial clinical value and may serve as cancer biomarkers." (PMID 38297161, 2024). "An extracellular secreted matrix protein, transforming growth factor beta-induced (TGFBI, originally named βig-h3), comprises 683 amino acids that have been shown to play a critical role in morphogenesis, differentiation, inflammation, tumor progression and metastasis and cell growth." (PMID 37759870, 2023). "Consequently, the unique upregulation of TGF‐beta family genes TGFB1, TGFBR2, TGFBI, TGFB1I1, and TGFB3 in S‐ECM could be due to increased production of TGF‐beta by CAFs in the tumor microenvironment." (PMID 36637997, 2023). "Furthermore, the expression of ICAM1 or TGFBI has been shown to be upregulated in TNBC and related to tumor aggressiveness and metastasis, and the expression of both genes were increased in TAB182 KD cells and participated in the cell adhesion process in the present study." (PMID 37953246, 2023). "TGFBI expression was markedly decreased in tumor regions lacking M2-like TAMs." (PMID 35673564, 2022). "However, we could just conclude that TGFBI is up-regulated in HNC and acts as a promoter in tumor progression." (PMID 26857387, 2016). "We pooled the data on all non-tumor patients and stratified them by age and gender, but neither of these 2 variables seemed to influence serum TGFBI levels (data not shown), suggesting that under the non-tumor condition, the age and gender do not influence the serum TGFBI levels." (PMID 25889002, 2015). "Similar to BXPC3 cells, the wound could not be closed in either tumor cells in the presence of TGFBI at study termination." (PMID 25369402, 2014). "In this study, by re-introduction of TGFBI into tumor cell lines MDA-MB-231 and NCI-H28, which have naturally low levels of TGFBI, we substantiated the role of TGFBI as a tumor suppressor and more importantly discovered previously unknown portions of its underlying mechanism." (PMID 22695319, 2012). "Therefore, we sought to understand the molecular mechanisms that influence TGFBI function and its interrelationship with other ECM components known to be present in the tumor microenvironment in order to better determine potential therapeutic targets and indicators of treatment response." (PMID 22640878, 2012). "In addition, the activities of check-point, tumor-infiltrating lymphocytes (TIL), chemokine C-C-Motif receptor (CCR), T-cell coinhibition, and type II interferon (IFN) response were markedly enhanced in the GDN subjects with low PRKAR2B expression or subjects with high TGFBI expression." (PMID 35663304, 2022). "Urinary detectable TGFBI and P4HB, but not VSIG4, were demonstrated to be higher expressed in patients with III-IV grade tumor than those with I-II grade tumor." (PMID 37035174, 2023). "Regardless of TGFBI expression status in the primary tumor (2/5 CRC samples were nearly negative), TGFBI was always strongly expressed in the matched CRC-LM samples." (PMID 33408771, 2021). "Although TGFBI did not completely block the formation of tumors derived from injection of MDA-MB-231 cells, the onset of tumor formation was delayed, tumor volume was greatly reduced, and the number of tumors decreased dramatically." (PMID 22695319, 2012). "In the RT-PCR data, we noticed that SOX4 and TGFBI appear to be almost mutually exclusive in the tumor samples, suggesting a possibility that GBM may achieve activation of the non-canonical TGF-β through either SOX4 or TGFBI." (PMID 20419098, 2010).
cancer (134 papers, 2002 to 2026). A tumor composed of atypical neoplastic, often pleomorphic cells that invade other tissues. "To further investigate the contribution of each gene, we focused on TGFBI, a top-ranked gene that plays a role in regulating extracellular matrix interactions and is implicated in cancer progression and metastasis." (PMID 40959565, 2025). "TGFBI, transforming growth factor beta-induced, is a protein linked to various types of cancer due to its role in the ECM and its interaction with integrins." (PMID 40510341, 2025). "We focused on the novelty of APOL1 as a potential cancer marker whose low expression strongly associated to poor survival rate at metastatic stage of ccRCC, considering that TGFBI had already been identified as oncogene in RCC." (PMID 38680858, 2024). "TGFBI, an extracellular matrix protein, has been implicated in modulating cell adhesion, migration, and proliferation in cancer." (PMID 39628390, 2024). "Herein, we proved that, in addition to controlling cancer cells, the loss of Cat D-mediated TGFBI expression was closely involved in TME control." (PMID 38297161, 2024). "Among them, TGFBI is closely associated with cancer metastasis, and miR675 can directly bind to the 3′UTR of TGFBI-mRNA to inhibit the normal translation of TGFBI." (PMID 36406273, 2022). "TGFBI protein overexpression is strongly associated with a more advanced tumor stage, metastasis and cancer-specific mortality in ccRCC patients." (PMID 35159281, 2022). "TGFBI expression was positively associated with stromal and immune scores in the pan-cancer analysis (all p < 0.05)." (PMID 34671645, 2021). "We assessed the associations between TGFBI expression and cancer survival outcomes in the TCGA database using GEPIA2." (PMID 34671645, 2021). "We selected 2 genes (UBE2C, TGFBI) with junctions that were associated with cancer and had overlap with junction data from the TCGA cohort for validation." (PMID 32437477, 2020). "Accordingly, elevated TGFBI levels have been associated with a broad variety of diseases, such as corneal disorders, nephropathy, rheumatoid arthritis, cancer and atherosclerosis." (PMID 31514337, 2019). "Loss of TGFBI expression is frequent in human cancer and it has been causally related to acquisition of tumorigenic phenotype in asbestos-treated immortalized human bronchial epithelial cells." (PMID 22695319, 2012). "TGFβI’s presence pushed cells into cellular senescence (with even telomerase activity paradoxically rising as often seen in stress-induced senescence), and conversely, loss of TGFBI was one factor allowing those cancer cells to escape senescence and continue dividing." (PMID 40791849, 2025). "MMP17, PI3, TLL1, ANGPTL4, and TGFBI have all been previously associated with cancer." (PMID 37388244, 2023). "TGFBI has been implicated in the pathogenesis of cancer and diabetic retinopathy." (PMID 36854775, 2023). "More recently, some cancers are associated with increased TGFBI expression." (PMID 35265561, 2022). "To investigate immune cell infiltration at the pan-cancer level, we used TIMER2.0 to explore the associations between TGFBI expression in human cancer and the infiltration of various types of immune cells (based on CIBERSORT, CIBERSORT-ABS, XCELL, MCPCOUNTER, QUANTISEQ, and EPIC algorithms)." (PMID 34671645, 2021).
cancer (continued). "In this study, we investigated the TGFBI expression, survival status, TGFBI mutations, immune cell infiltration, and associated molecular pathways, to explore the potential cellular mechanisms of TGFBI in various types of cancers." (PMID 34671645, 2021). "Collectively, these meta-analyses suggest that in a given tissue, aggregated expression of FN1, TGFBR2, TGFB2, and TGFBI might serve as an index for the extent of cancer-associated fibroblasts (CAFs)." (PMID 32605311, 2020). "Because EMT is a crucial step of metastasis, it is of great interest to examine whether TGFBI expression is associated with the clinical outcome of cancer patients." (PMID 30967542, 2019). "More recently, the TGFBI gene has been found to be frequently associated with cancer development." (PMID 22695319, 2012). "Moreover, we explored the impact of somatic TGFBI mutations in human cancer." (PMID 34671645, 2021). "The multifaceted contribution of TGFBI in a range of pathologies ranging from cancer to degenerative diseases is evident." (PMID 39752341, 2025). "Previous studies have reported that TGFBI is secreted from fibroblasts and cancer, endothelial, and immune cells and regulates their activity and function." (PMID 38297161, 2024). "Elevated TGFBI expression in Cat D KO cancer cells resulted in a decline in M2-like TAM polarization." (PMID 38297161, 2024). "Our observations indicated that Cat D deletion in cancer cells skewed TMA polarization to the anticancer M1 phenotype through TGFBI overexpression." (PMID 38297161, 2024). "In contrast, in the C57BL/6 strain, Cat D and TGFBI double deletion completely reversed the anti-metastatic effect of the Cat D KO cancer cells." (PMID 38297161, 2024). "In summary, we confirmed our previously identified methylation biomarkers ALOX5, TRPS1 and Chromosome 16 as well as our protein biomarkers CXCL16 and TGFBI to discriminate UCa from cancer-free controls in a large and independent collective." (PMID 39587670, 2024). "Our loss-of-function data proved that Cat D is a positive regulator of EMT in cancer and showed an inverse correlation with TGFBI expression in various types of cancer cells." (PMID 38297161, 2024). "Like TGFβ, TGFBI either inhibits or promotes tumorigenesis depending on the different types of cancers." (PMID 38245723, 2024). "We observed decreased CCL20 expression in Cat D KO cancer cells, which increased following TGFBI blockade." (PMID 38297161, 2024). "Studies have widely reported that KRT4, IGFBP3, MMP10, MMP3, and TGFBI are involved in the pathogenesis of LC and other cancers." (PMID 38302910, 2024). "Conversely, TGFBI depletion reduces sphere formation and suppresses the expression of cancer stem cell (CSC) markers." (PMID 38514830, 2024). "This pancancer gene set includes key integrins (e.g. ITGA6, ITGB1, ITGB4) and their interconnectors (e.g. SPP1, TGFBI), affirming their critical role in the cancer adhesion resistome." (PMID 37206618, 2023). "The lipopolysaccharide-positive group showed increased cancer stromal TGFBI expression (p < 0.0001) and PD-L1 expression in cancer cells (p = 0.0029)." (PMID 37511547, 2023). "A recent pan cancer study indicated TGFBI as a prognostic marker in various cancers due to its involvement in various immune responses." (PMID 36463238, 2022). "Previous reports indicated TGFBI exerted biological function via binding the integrins located on the cellular surface in other cancers 46-48." (PMID 35673564, 2022). "Comparison of changes in infection- and exposure-specific methylomes led to the identification of a shared epigenetic mechanism culminating in the transcriptional silencing of a cancer-related gene, TGFBI." (PMID 35267594, 2022).
cancer (continued). "The associated cancer functional states of hsa-mir-21 predicted target genes (RP2, NFIA, SPRY1 and TGFBI) was first revealed." (PMID 36035369, 2022). "The transcriptional expression of RP2, NFIA, SPRY1 and TGFBI in four cancer stages was significantly higher than that of the normal." (PMID 36035369, 2022). "Overall, our results provide evidence for the role of TGFBI as a potential cancer-related gene affected by EBV infection and AFB1 exposure-associated hypermethylation." (PMID 35267594, 2022). "The role of TGFBI is dependent on cellular context as its expression is elevated or suppressed in many cancers." (PMID 36463238, 2022). "For the analysis of 24 immune-inhibiting genes, we found that SERPINH1 expression was highly associated with CD276, TGFBI, VEGFA, HAVCR2, IL10, and ADORA2A in most cancers." (PMID 36105106, 2022). "We have provided new clues for improving cancer diagnosis and developing cancer immunotherapies that target TGFBI." (PMID 34671645, 2021). "TGFBI is involved in immune cell infiltration and inflammatory responses, which play key roles in cancer initiation, progression, and metastasis." (PMID 34671645, 2021). "Other information on the role of TGFBI in cancer generally points to a tumor-promoting role, although Tgfbi null mice, which have retarded growth, also have an increased incidence of spontaneous and carcinogen-induced cancers." (PMID 34561272, 2021). "Increased TGFBI mRNA expression positively correlates with the transition from normal colon to cancer." (PMID 33408771, 2021). "As an extracellular matrix protein, TGFBI is closely related to the development of different malignant tumors." (PMID 34217310, 2021). "Here, we found that TGFBI expressed by metastatic CRC cells has a pro-tumorigenic function by affecting the crosstalk between cancer and endothelial cells, resulting in enhanced angiogenesis." (PMID 33408771, 2021). "Using the Cancer Regulome Explorer website, we investigated the relevant genomic correlation between TGFBI gene and certain signatures." (PMID 34671645, 2021). "In this study, we conducted a pan-cancer analysis of TGFBI mRNA and protein expression and prognoses of various cancer types using public databases." (PMID 34671645, 2021). "We also applied GEPIA2 to analyze TGFBI expression in various pathological stages of multiple cancer types." (PMID 34671645, 2021). "The detection of periostin (POSTN) and transforming growth factor beta-induced protein (TGFBI), two circulating biomarkers overexpressed by cancer stem cells, is achieved in cancer patient serum with the use of the device." (PMID 33806753, 2021). "Since our results have confirmed the immunoregulation role of the TGFBI in various types of cancer, it is vary needed to explore further the correlation between TGFBI expression and TME." (PMID 34671645, 2021). "CM from TGFBI-silenced cancer cells significantly decreased HUVEC proliferation, migration and sprouting." (PMID 33408771, 2021). "The results showed that TGFBI expression varied among different cancer types, and it was positively or negatively related to prognosis in various cancers." (PMID 34671645, 2021). "In multivariate Cox analysis interacting with cancer recurrence, TGFBI and HYAL1 remained statistically significant for poor and good prognosis, respectively." (PMID 34869001, 2021). "As previous studies reported that TGFBI can either promote or inhibit progression of different cancer types, it was important to verify TGFBI effect in our CRC models." (PMID 33408771, 2021). "To investigate the potential relationships between TGFBI expression and drug responses in various types of human cancer, we performed a correlation analysis to identify potential drug candidates using CellMiner." (PMID 34671645, 2021). "To confirm that TGFβ signaling (and hence TGFBI expression) was stronger in cancer cells from metastatic than from primary CRC, we analyzed primary CPPs isolated from CRC and CRC-LM samples." (PMID 33408771, 2021).